ALK (ALK receptor tyrosine kinase)
Diseases named in the same sentence as ALK in open-access papers (continued):
Sharing a sentence is not in itself a finding about the gene and the disease.
neuroblastoma (continued). "Extending the concept of collateral sensitivities, we identified MEK inhibitor hypersensitivity as a new vulnerability after NF1 loss in ALK-mutated neuroblastoma cells." (PMID 35689207, 2022). "Anaplastic lymphoma kinase (ALK) is a kinase implicated in tumoral processes, mainly lymphomas and neuroblastomas." (PMID 36558915, 2022). "In the current study, we present two clinical cases and one paired neuroblastoma cell line where ALK mutations were lost at relapse while other genetic abnormalities were maintained." (PMID 36029175, 2022). "At diagnosis, up to 15% of neuroblastomas harbor activating point mutations or amplifications of ALK, and ALK mutations are further enriched upon disease relapse." (PMID 35689207, 2022). "Eventually, it became evident that different ALK hotspot mutations in neuroblastoma confer differential sensitivity toward different ALK inhibitors." (PMID 35362827, 2022). "ALK amplification or mutation was identified in ∼14% of neuroblastomas (NBs), the most common extracranial childhood tumour." (PMID 35508387, 2022). "As previously reported for neuroblastoma, the mutation frequencies were generally low, with ALK (9%), PTPN11 (3%) and ATRX (3%) mutations being the most common." (PMID 36175618, 2022). "In contrast to previous reports of gain of ALK mutations at relapse in neuroblastoma, here we present two cases where hotspot ALK mutations were lost at relapse." (PMID 36029175, 2022). "Genome-wide forward genetic CRISPR-Cas9 based screens were performed to identify genes associated with ALK inhibitor resistance in neuroblastoma cell lines." (PMID 35689207, 2022). "By contrast, we did not observe significant synergistic effects of 6-thio-dG in combination with the ALK inhibitor ceritinib, both in ALK-mutated and ALK-wildtype neuroblastoma cells." (PMID 35953764, 2022). "ALK is the most commonly mutated oncogene in neuroblastoma with increased mutation frequency reported at relapse." (PMID 36029175, 2022). "Here we report the loss of an ALK mutation in two patients at relapse and a paired neuroblastoma cell line at relapse." (PMID 36029175, 2022). "One study indicated that PHOX2B directly regulates ALK transcription, thereby providing a direct link between these two neuroblastoma predisposition genes." (PMID 36140661, 2022). "In line with our in vitro data, we detected de novo NF1 and NRAS or HRAS mutations in neuroblastomas from patients treated with the ALK inhibitors, ceritinib or lorlatinib, at resistance development." (PMID 35689207, 2022). "ALK mutations are present in 8%–14% of all neuroblastomas at diagnosis, increasing to 26%–43% at relapse." (PMID 36029175, 2022). "In conclusion, only NF1 loss but not the expression of oncogenic NRASQ61K seems to trigger loss of feedback-mediated MEK reactivation and leads to increased sensitivity of neuroblastoma cell lines harboring ALK mutations to MEK inhibition." (PMID 35689207, 2022). "The respective mutation frequencies were similar to that of North American neuroblastoma patient populations that were interrogated with whole exome sequencing (WES) (ALK, 8% versus 9.2%; ATRX, 3% vs 2.5%)." (PMID 35768791, 2022). "Mutated ALK is a driving oncogene in neuroblastoma, and neuroblastoma cells have a persistent and strong dependency on mutated ALK." (PMID 35689207, 2022). "Despite multimodal therapy including chemotherapy, surgery, radiation therapy and immunotherapy, high-risk neuroblastoma, often harboring ALK alterations, remains very difficult to treat." (PMID 35689207, 2022). "ALK mutations are the leading cause of hereditary neuroblastoma, but also one of the most common somatic mutations." (PMID 36029175, 2022). "In high-risk neuroblastoma, the commonest somatic variants encountered include ALK, PTPN11, and ATRX." (PMID 35768791, 2022).
neuroblastoma (continued). "Further research into clonal evolution of neuroblastoma in patients whose tumors lose ALK mutations at relapse and those with CNS relapse using clonal metastatic reconstruction and single cell analysis is required to understand this further." (PMID 36029175, 2022). "To date, the ALK mutation status of ~150 paired diagnosis and relapse neuroblastoma cases have been reported, alongside around 90 of our cases." (PMID 36029175, 2022). "The “anaplastic lymphoma tyrosine kinase” receptor, ALK, is altered by gain-of-function point mutations in half of familial neuroblastoma cases (~ 1% of total cases), and in around 9% of sporadic neuroblastoma, climbing up to 14% in high-risk patients." (PMID 34716856, 2022). "To formally demonstrate that loss of NF1 can cause ALK inhibitor resistance in neuroblastoma cell lines, we generated several neuroblastoma cell line models harboring NF1 knockouts." (PMID 35689207, 2022). "In a mouse xenograft model of neuroblastoma with ALK F1174L and F1245C mutations, the CDK4/6 inhibitor ribociclib blocks the binding of CDK4/6 to CyclinD1, thereby inhibiting the operation of the cell cycle." (PMID 35211406, 2022). "This demonstrates that NRASQ61K mutation is sufficient to induce an ALK inhibitor resistant phenotype in neuroblastoma cell lines." (PMID 35689207, 2022). "Except predisposing to neuroblastoma, germline ALK mutations have rarely been associated with other developmental anomalies." (PMID 36140661, 2022). "Of the 34 neuroblastoma patients, 11 had ALK mutations; in this group, one patient had a complete response and two had a stable disease response." (PMID 34769519, 2021). "Another important molecular event thought to participate in MYCN amplification is the presence of ALK mutations in neuroblastoma." (PMID 34842635, 2021). "In high-risk neuroblastoma, ALK mutations co-segregate with MYCN amplification, with the ALK mutation driving its transcription and expression." (PMID 34298746, 2021). "The overall survival of patients with mutated ALK is lower, making ALK aberrations prognostic biomarkers of lower survival in neuroblastoma." (PMID 34591871, 2021). "ALK mutations are the most frequently observed somatic mutations in neuroblastoma, with either point mutations, amplification or fusion events occurring in 7–10% of cases." (PMID 34064704, 2021). "In ALK-mutated neuroblastoma cells, CCC-003 significantly reduced the mRNA and protein expression levels of ALK in a dose-dependent manner." (PMID 34591871, 2021). "Further, gain-of-function mutations and ALK overexpression are associated with both familial and sporadic neuroblastoma disease." (PMID 34591871, 2021). "These two autoinhibitory interactions are disrupted by activating mutations (e.g. F1174L, R1275Q) in ALK in neuroblastoma that drive kinase activity." (PMID 34661367, 2021). "In neuroblastoma, activating mutations in ALK are found in both familial and sporadic forms, where they are now appreciated to be present in around 10% of primary cases." (PMID 34885007, 2021). "ALK genetic abnormalities (mutation or amplification) have been associated with high-risk neuroblastoma, with tumours often composed of undifferentiated neuroblasts instead of differentiated neuronal cells." (PMID 34769149, 2021). "Our results support previous findings in small cohort cases of ALK variants in the circulation of patient with neuroblastoma." (PMID 34282791, 2021). "ALK is the gene more frequently mutated in sporadic neuroblastoma, as well as in the germline of familial neuroblastoma patients." (PMID 34957126, 2021). "Anaplastic lymphoma kinase (ALK) aberration is related to high-risk neuroblastomas and is an important therapeutic target." (PMID 34591871, 2021). "Although rare, there has been little investigation of ALK extracellular mutations or other ALK aberrations in patient samples, although several neuroblastoma derived cell lines are known to harbor ALK extracellular domain variants that are activating." (PMID 34885007, 2021).
neuroblastoma (continued). "ALK is mostly associated with neuroblastoma, the most common and lethal extracranial solid tumour of infancy, causing 15% of childhood cancer-related deaths." (PMID 34020009, 2021). "At 48 h after treatment, CCC-003 significantly increased the number of Annexin V-positive SH-SY5Y and Kelly cells in a dose-dependent manner, while the mismatch polyamide had little influence on the viability of ALK-mutated neuroblastoma cells." (PMID 34591871, 2021). "As observed in cell lines, the most frequently mutated single gene except for MYCN was ALK, with SNVs in 5 neuroblastomas and a gain in 1 neuroblastoma." (PMID 34442335, 2021). "F1174L-mutated ALK expression was previously demonstrated to have an anti-apoptotic effect during neuroblastoma genesis." (PMID 34591871, 2021). "The mechanism of ALK amplification in neuroblastoma is attributable to gene amplification or ALK mutations." (PMID 33466277, 2021). "The RAS/MAPK pathway is frequently deregulated in many cancer types, including neuroblastoma, due to activating mutations in ALK/RAS/RAF or inhibitory NF1 mutations or deletions." (PMID 34572875, 2021). "This was confirmed in a study on ALK mutations in neuroblastoma patients, in ALK-TKI resistant NSCLC patients and subjects suffering from myofibroblastic tumors." (PMID 33572278, 2021). "This is in keeping with previous analyses of neuroblastoma cases, which identified a correlation between coexistence of ALK activating mutations and MYCN amplification in high-risk neuroblastoma with poor prognosis." (PMID 34885007, 2021). "Crizotinib has also shown activity in some pediatric patients with ALK point mutations or amplification (>10 copies), which are observed in 14% of neuroblastoma patients and associated with the worse outcomes." (PMID 34298746, 2021). "In more recent years it became clear that mutations of the ALK tyrosine kinase domain constitute an important potential therapeutic target in neuroblastoma and can be detected in ctDNA." (PMID 34282791, 2021). "Heterogeneity at the ALK locus is found in almost all familial neuroblastoma cases and is associated with poor prognosis in sporadic cases." (PMID 34769149, 2021). "Among activating mutations, F1174L has been reported to confer resistance to ALK inhibitor crizotinib in neuroblastoma." (PMID 34591871, 2021). "Several groups have reported that MYCN and ALK gain-of-function mutations, either in locus or overexpressed, cooperate to drive transformation, and result in increased neuroblastoma penetrance in both cell line—mouse and zebrafish—models." (PMID 34885007, 2021). "Sympathoadrenal progenitor cells express anaplastic lymphoma kinase (ALK), which encodes a tyrosine kinase receptor that is the most frequently mutated gene in neuroblastoma." (PMID 34769149, 2021). "S5A), in particular, the two most common neuroblastoma predisposition genes, ALK and PHOX2B, and the cancer gene MYCN, somatic amplification of which is a key adverse marker used clinically for neuroblastoma risk stratification." (PMID 33547074, 2021). "In neuroblastoma, most ALK mutations occur within the kinase domain with two mutation hotspots at F1174 and R1275." (PMID 34591871, 2021). "CCC-003 exhibited anti-proliferative effects in ALK mutation-positive neuroblastoma in vitro and in vivo." (PMID 34591871, 2021). "The satisfactory therapeutic effects of crizotinib can be observed by treating inflammatory myofbroblastic tumors with ALK rearrangement and neuroblastoma with R1275Q mutation in ALK." (PMID 34976824, 2021). "CCC-003 was designed to directly bind to and alkylate DNA within the F1174L-mutated ALK gene in neuroblastoma cells." (PMID 34591871, 2021). "In analogous works in high-risk neuroblastoma, molecularly selected patients are treated in an ongoing study with the ALK inhibitor ceritinib combined with the CDK4/6 inhibitor ribociclib based on preclinical evidence of synergy (NCT02780128)." (PMID 34298746, 2021).
neuroblastoma (continued). "In relapsed neuroblastoma cases, mutations are more frequently observed in ALK, as well as other well-known oncogenes and tumor suppressor genes, such as NF1, RAS, and RAF, and also PTPN11 and FGFR." (PMID 34885007, 2021). "A fraction (up to 10%) of sporadic neuroblastomas and virtually all familial cases are characterized by ALK activating point mutations or gene amplification." (PMID 34680298, 2021). "ALK mutations were detected in 33 neuroblastomas, with R1275Q mutations in 14 and F1174L mutations in 10 cases." (PMID 34442335, 2021). "A 15-year-old patient with stage 3 NBL (according to the International Neuroblastoma Staging System) and an ALK F1245C point mutation relapsed 11 months after treatment with the NBL high-risk regimen." (PMID 34575503, 2021). "The anaplastic lymphoma kinase (ALK) gene is known to be one of the factors related to the prognosis of neuroblastoma, and mutations of this gene are related to high-risk neuroblastoma." (PMID 34591871, 2021). "Familial neuroblastoma has been shown to be caused by somatic mutations in anaplastic lymphoma kinase (ALK)." (PMID 34354842, 2021). "Its impact against neuroblastoma through targeting ALK mutations or TRK-B expression is under further investigation." (PMID 34298746, 2021). "Although, ALK is a known predisposition gene for neuroblastoma development, we are still far from understanding its role in tumour initiation." (PMID 34769149, 2021). "For example, in each neuroblastoma tumour sample, a mutation was present in only one out of five putative driver genes—ALK, ATRX, PTPN11, MYCN or NRAS." (PMID 34434669, 2021). "Recent advances with ALK and Trk inhibitors have demonstrated a potential to benefit subsets of high-risk neuroblastoma patients." (PMID 34064704, 2021). "Several groups have shown that ALK gain-of-function mutations are unable to drive neuroblastoma alone when ALK is expressed at endogenous levels." (PMID 34885007, 2021). "Recent whole genome sequencing analysis in a large cohort of neuroblastoma patients have identified a paucity of recurrent alterations with point mutations in ALK (8–10%) and in ATRX, being the most frequent." (PMID 33381456, 2020). "In a large part of these familial neuroblastomas, germline mutations of the ALK (anaplastic lymphoma kinase) gene can be detected." (PMID 32252464, 2020). "The presence of ALK point mutations, occurring in 8–10% of sporadic neuroblastoma, serve as biomarker of therapeutic sensitivity to small-molecule kinase inhibitors that are currently undergoing clinical assessment in phase I and II trials." (PMID 33381456, 2020). "These neuroblastoma cells harbour the activating NRASQ61K mutation in a wild-type ALK cellular background." (PMID 31937834, 2020). "In a recent study, entrectinib produced favorable responses in children and adolescents with refractory CNS and extracranial solid tumors harboring NTRK, ROS1, or ALK fusions, as well as those with ALK-mutated neuroblastoma." (PMID 33109256, 2020). "ALK mutations can be detected in all clinical stages while an association with a poorer outcome can only be detected in intermediate- and high-risk neuroblastoma." (PMID 33585251, 2020). "Functionally, the oncogenic role of ALK mutations has only been demonstrated in neuroblastoma, in particular ALK F1174C/I/L/S/V, F1245C/I/L/V, and R1275L/Q mutations." (PMID 32059449, 2020). "Despite that several molecular prognostic factors with oncogenic potentials have been described in neuroblastoma, only activating ALK mutations and MYCN overexpression were shown to be de novo oncogenic drivers." (PMID 33585251, 2020). "Gain-of-function mutations (e.g., F1174L or R1275Q) in ALK were first identified in neuroblastoma and induce constitutive autophosphorylation of ALK." (PMID 32300555, 2020). "Variant rs1670283 (ALK) is associated with the hereditary cancer-predisposing syndrome and neuroblastoma 3 (NCBI ClinVar)." (PMID 32708070, 2020).
neuroblastoma (continued). "Anaplastic lymphoma kinase (ALK) belongs to the family of tyrosine kinases and is regarded as a potential target for the treatment of neuroblastomas as ALK gene mutations and overexpression is frequently observed in neuroblastoma patients." (PMID 32244744, 2020). "Germline and somatic ALK kinase-domain point mutations have been detected in familial and sporadic neuroblastoma, respectively." (PMID 33056981, 2020). "A second analysis in this cohort separating neuroblastomas harbouring either mutant ALK (ALKmut) or mutations in other RAS/MAPK pathway genes (RAS/MAPK mutwithout ALK) also revealed significant differences compared to wild-type backgrounds." (PMID 31937834, 2020). "We identified ETV5, a bona fide oncogene in prostate cancer, as robustly upregulated in neuroblastoma cells harbouring ALK mutations, and show high ETV5 levels downstream of the RAS/MAPK axis." (PMID 31937834, 2020). "COSMIC mutational signature 18, previously associated with reactive oxygen species, is the most common cause of driver point mutations in neuroblastoma, including most ALK and Ras-activating variants." (PMID 33056981, 2020). "Detailed molecular characterization of the neuroblastoma genomic landscape indicates that ALK-activating mutations are present in 10% of primary tumours." (PMID 31937834, 2020). "High ALK gene expression values have been associated with neuroblastoma formation, and the presence of non-small cell lung cancers (NSCLC)." (PMID 33062421, 2020). "Activating ALK mutations combined with MYCN amplifications in neuroblastoma is associated with very poor prognosis in patients, which is mirrored by the finding that ALK mutation accelerates tumour formation in animal models of MYCN-driven neuroblastoma." (PMID 31937834, 2020). "Regarding the possible extension of our findings to other ALK-dependent cancers, ALK inhibition in ALK-mutated neuroblastoma or ALK overexpressing rhabdomyosarcoma has been proposed to activate autophagy associated with cell death." (PMID 33066037, 2020). "Recent studies on familial neuroblastoma, which is rare, have also identified ALK and PHOX2B gene mutations." (PMID 30658459, 2019). "ALK mutations occur in 9% of primary tumors but this percentage is increased in the relapsed neuroblastoma patient population." (PMID 31334113, 2019). "To extend our analysis, we examined the ability of alectinib to inhibit ALK gain of function variants found in neuroblastoma." (PMID 31334113, 2019). "IC50 values of pALK-Y1604 inhibition by either alectinib or crizotinib treatment after 4 h in PC12 cells for ALK-wt and the indicated ALK neuroblastoma mutant variants." (PMID 31334113, 2019). "Altogether, this study provides novel insights into ALK mutation dynamics in a neuroblastoma model harbouring two ALK mutations." (PMID 31452835, 2019). "In hereditary neuroblastoma, a mutation at the R1275 locus of ALK can be treated using the first-generation ALK inhibitor, Crizotinib." (PMID 35582571, 2019). "In neuroblastoma, different ALK mutations have been shown to exhibit different activation levels and response to crizotinib." (PMID 31452835, 2019). "ALK mutations are found in around 9% of all neuroblastomas at diagnosis, with the incidence increasing to 14% in the high-risk subtype." (PMID 35582571, 2019). "These initial findings led us to perform an extensive analysis of different ALK mutant variants found in neuroblastoma in the context of the full-length receptor." (PMID 31334113, 2019). "A screen of known neuroblastoma-associated ALK mutations utilizing recombinant ALK variants, revealed that response to crizotinib correlated with a relatively reduced affinity of the mutant kinase for ATP." (PMID 35582571, 2019).